APOL1 (apolipoprotein L1)
Diseases named in the same sentence as APOL1 in open-access papers (continued):
Sharing a sentence is not in itself a finding about the gene and the disease.
latent infection (3 papers, 2017 to 2018). "In this study, we found that the 6 base pair deletion in APOL1 G2 is risk factor for developing an active T. b. gambiense infection from a latent infection." (PMID 28827791, 2017). "Subjects carrying the APOL1 G1 (p = 0.0005, OR = 0.45, CI95 = [0.29–0.70], BONF = 0.0129) had an increased risk of developing a latent infection but reduced risk of progressing from latent infection to active HAT than APOL1 G0." (PMID 28827791, 2017). "The strongest association was with APOL1 rs73885319, which is also known as the G1 allele, which had a 90% chance of being a true positive in the comparison between latent infections and controls." (PMID 29059176, 2017). "The main findings of our study are that the A allele of IL6 rs1818879 and the G allele of APOL1 G1 appear to be associated with a higher risk of developing a latent infection but a lower risk of progressing from latent infection with undetectable parasitaemia to active disease." (PMID 28827791, 2017). "However, the APOL1 G2 allele increased the risk of progressing from latent infection to active HAT." (PMID 28827791, 2017). "The distribution of APOL1 G1 and APOL1 G2 in the present study were significantly different in latent infections compared to both cases and controls." (PMID 28827791, 2017). "There were suggestive associations at three loci in IL6 and TNFA in the comparison between active cases and controls, one SNP in each of APOL1, MIF and IL6 in the comparison between latent infections and active cases and seven SNP in IL4, HLA-G and TNFA between latent infections and controls." (PMID 29059176, 2017).
lung adenocarcinoma (3 papers, 2021 to 2024). A carcinoma that arises from the lung and is characterized by the presence of malignant glandular epithelial cells. "This event leads to the upregulation of APOL1, and is associated with poor overall survival of lung adenocarcinoma." (PMID 38680858, 2024). "Univariate Cox regression analysis suggested that the high expression levels of up-regulated DEGs including APOL1, ETFB, KLK8, PPP1R3G, PRL, and SPTA1 were significantly correlated with poorer overall survival (OS) in lung adenocarcinoma." (PMID 38183079, 2024).
myocardial infarction (3 papers, 2019 to 2025). Gross necrosis of the myocardium, as a result of interruption of the blood supply to the area, as in coronary thrombosis. "A prospective investigation conducted over two decades in older adults suggested that the APOL1 genotype was associated with albuminuria, peripheral atherosclerosis, risk of myocardial infarction and death." (PMID 38017264, 2023).
renal dysfunction (3 papers, 2018 to 2023). "However, SYPL2-rs12136063 as well as APOL1 (G1)-rs73885319 conferred increased risk of progressing to the renal dysfunction or to prevalent glomerular hyperfiltration, explaining 11.04 and 0.97% of status changes, respectively." (PMID 33790942, 2021). "This study has replicated APOL1 gene variants: (G1)-rs73885319 and (G2)-rs71785313, shown to be strongly associated with renal dysfunction in SCD patients, as well as A1CF-rs10994860, SYPL2-rs12136063, WNT7A-rs6795744, and TMEM60-rs6465825 in Cameroonian SCD patients." (PMID 33790942, 2021).
renal fibrosis (3 papers, 2019 to 2025). A final common manifestation of a wide variety of chronic kidney diseases characterized by glomerulosclerosis and tubulointerstitial fibrosis. "In the present study, TGF-β, a key mediator of renal fibrosis, was also markedly upregulated in G2/G2 kidneys, particularly under NMP, though its direct mechanistic link to APOL1 remains less defined." (PMID 41010023, 2025).
Alport syndrome (2 papers, 2023 to 2025). A rare renal disease characterized by glomerular nephropathy with hematuria progressing to end-stage renal disease (ESRD), frequently associated with sensorineural deafness, and occasionally with ocular anomalies. "Of these, variants in COL4A3/4/5 (associated with Alport syndrome spectrum) comprised 31.8% of positive cases, and APOL1 high-risk genotypes comprised 45.5%." (PMID 37794564, 2023). "The other 7 positive tests included amyloidosis (TTR, N = 3), Alport syndrome (COL4A3, N = 2), polycystic kidney disease (PKD1, N = 1), and susceptibility to ESRD (APOL1, N = 1)." (PMID 40126616, 2025).
arterial disease (2 papers, 2015 to 2020). "Large vessel arteriosclerosis was similar in both races, but African Americans had significantly greater small arterial disease, a finding together with glomerular loss, which was previously shown to be associated with APOL1 risk alleles." (PMID 31599090, 2020).
Autoimmunity (2 papers, 2025). The occurrence of an immune reaction against the organism's own cells or tissues. "The G1 and G2 variants of APOL1 are strongly associated with the risk of developing CG, either idiopathic or secondary to exposure to triggers such as infections (HIV, HCV, parvovirus) or autoimmunity." (PMID 39792859, 2025).
breast carcinoma (2 papers, 2016 to 2022). "In summary, our works demonstrate that 4 autophagy-related mRNA (APOL1, HSPA8, SIRT1, and TP73) are significantly associated with the early relapse of breast cancer during the postoperative follow-up." (PMID 35250881, 2022).
Dengue (2 papers, 2024 to 2025). "Dengue pathogenesis therefore strongly supports dengue infection as a potential second hit for APOL1-mediated kidney diseases, triggering the disease in the setting of APOL1-HRG." (PMID 41278320, 2025).
depression (2 papers, 2022 to 2024). "Apolipoprotein L1 (APOL1) in plasma was found to be suggestively associated with self-reported depression in our study." (PMID 35870967, 2022). "Hence, it can be inferred that APOL1 may induce abnormal function in the hippocampus, and may play a vital role in depression development." (PMID 35870967, 2022).
head and neck squamous cell carcinoma (2 papers, 2024). A squamous cell carcinoma that arises from any of the following anatomic sites: lip and oral cavity, nasal cavity, paranasal sinuses, pharynx, larynx, and salivary glands. "In addition, APOL1 is highly expressed in head and neck squamous cell carcinoma tissues and thyroid cancer tissues." (PMID 38410113, 2024).
heart failure (2 papers, 2024 to 2025). Inability of the heart to pump blood at an adequate rate to meet tissue metabolic requirements. "We suspect that differences in cardiac function would be particularly apparent in a model of heart disease such as heart failure with preserved ejection fraction (HFpEF), and suggest future research focuses on the effect of murine APOL1 genotype in HFpEF and related conditions." (PMID 41497611, 2025).
Hydrocephalus (2 papers, 2024 to 2025). Hydrocephalus is an active distension of the ventricular system of the brain resulting from inadequate passage of CSF from its point of production within the cerebral ventricles to its point of absorption into the systemic circulation. "Although infection is the major cause of infant hydrocephalus, the role of APOL1 high-risk variants in hydrocephalus needs further investigation." (PMID 40459058, 2025). "Hydrocephalus imposes a heavy disease burden in sub-Saharan Africa, with ~200,000 estimated new cases annually among a population of 1.2 billion; this is also a region where APOL1 high-risk variants are common." (PMID 40459058, 2025). "To determine whether hydrocephalus prevalence was higher in individuals with APOL1 high-risk variants, we made use of the All of Us cohort data." (PMID 39803526, 2024). "The hydrocephalus was communicating and likely was due to excess cerebrospinal fluid produced by the choroid plexus, where epithelial cells expressed APOL1." (PMID 39803526, 2024). "While APOL1-G1 expression in ApoE-KO mice did not worsen CVD phenotypes, we uncovered hydrocephalus as a novel APOL1 risk allele-mediated phenotype." (PMID 40459058, 2025). "While APOL1-G1 expression in ApoE-KO mice did not worsen cardiovascular disease phenotypes, we uncovered hydrocephalus as a novel APOL1 risk allele-mediated phenotype." (PMID 39803526, 2024). "APOL1 protein circulating in CSF may also play a role in hydrocephalus formation." (PMID 40459058, 2025). "APOL1 protein circulating in CSF71 may also play a role in hydrocephalus formation." (PMID 39803526, 2024).
hyperglycaemia (2 papers, 2019 to 2021). "In particular, the correlation between APOL1, triglycerol levels and hyperglycaemia only reflects APOL1 association with very low‐density lipoprotein particles, without known causality relationship." (PMID 32530132, 2021). "We postulated that insulin, not hyperglycemia, promoted ApoL1 secretion in the Mets liver." (PMID 31619724, 2019). "ApoL1 was significantly lower in T2DM without Mets, wherein c-peptide also presented the significant decrease despite of hyperglycemia, thus indicating β cell dysfunction in this group." (PMID 31619724, 2019).
injury (2 papers, 2018 to 2022). Damage inflicted on the body as the direct or indirect result of an external force, with or without disruption of structural continuity. "Thus, UTI may be a putative environmental risk factor responsible for APOL1-induced kidney injury." (PMID 29903699, 2018).
liver cancer (2 papers, 2014 to 2016). An epithelial or non-epithelial malignant neoplasm that arises from the liver. "One such example, APOL1 displays copy number loss in 73.8% of ovarian cancers and 33.5% of tumors of the large intestine, but is not subject to genetic inactivation in liver cancer, based on the Catalogue of Somatic Mutations in Cancer (COSMIC,)." (PMID 25294808, 2014).
liver fibrosis (2 papers, 2014 to 2016). "APOL1 has also been identified as a plasma biomarker for HCV-induced liver fibrosis and variants are cytotoxic in rat hepatocytes, in part, regulated by autophagy." (PMID 27054572, 2016). "Furthermore, hydrodynamic gene delivery of APOL1 G1 and G2 variants caused liver necrosis in mice, and APOL1 is a biomarker for HCV-induced liver fibrosis." (PMID 27054572, 2016). "Indeed, among the notable hypermethylated genes unveiled in this study is APOL1, a member of a family of programmed cell death genes that initiates apoptosis, which has been demonstrated to be a biomarker for liver fibrosis." (PMID 25294808, 2014).
Opportunistic infection (2 papers, 2021 to 2024). An infection that is caused by a pathogen that would generally not be able to cause an infection in a host with a normal immune system. "We next validated this finding in three other independent HIV-seroprevalent cohorts (LSOCA, MACS, and WIHS) by conducting a meta-analysis of the APOL1 variant allele’s effect on opportunistic infections." (PMID 33674766, 2021). "In summary, this population genetic study suggested that APOL1 might confer carriers of two variant alleles’ protection from HIV-related opportunistic infections, especially fungal infections." (PMID 33674766, 2021). "The study suggests that APOL1 might confer carriers of two variant alleles protection from HIV related opportunistic infections, especially fungal infections." (PMID 33674766, 2021). "The impact of APOL1 G1-G2 variants on HIV-1-associated opportunistic infections (OIs) is unknown." (PMID 33674766, 2021). "We evaluated whether APOL1 variant alleles might be protective against opportunistic infections." (PMID 33674766, 2021).
osteoporosis (2 papers, 2012 to 2024). A condition of reduced bone mass, with decreased cortical thickness and a decrease in the number and size of the trabeculae of cancellous bone (but normal chemical composition), resulting in increased fracture incidence. "We found that serum paraoxonase/arylesterase 1 (PON1) was positively associated with osteoporosis in East Asian, while cholinesterase (BCHE) was significantly associated with LS‐BMD, and apolipoprotein L1 (APOL1) was significantly associated with FN‐BMD and heel eBMD in European population." (PMID 37970652, 2024).
thyroid cancer (2 papers, 2024 to 2025). "Although apolipoprotein 1 (APOL1) expression is upregulated in several types of cancers, including thyroid cancer (THCA), its specific role in THCA remains unclear." (PMID 41378287, 2025). "Consequently, the high expression of APOL1 and its association with a favorable prognosis in thyroid cancer does not contradict its oncogenic potential, but rather highlights its complex and multifaceted regulatory roles in tumor progression." (PMID 41378287, 2025).
Arrhythmia (1 paper, 2026). Any cardiac rhythm other than the normal sinus rhythm. "However, current studies primarily focus on the variants of APOL1 associated with CVDs, with a limited number of studies examining arrhythmia." (PMID 41541644, 2026). "Thus, we found novel connections between CKD, the APOL1 gene, and CCDs among persons of African ancestry, which would benefit the management of cardiac arrhythmia in patients with CKD." (PMID 41541644, 2026). "Therefore, we provided new insights into the APOL1 gene’s role in arrhythmia and CKD." (PMID 41541644, 2026).
Bardet-Biedl syndrome (1 paper, 2024). A ciliopathy with multisystem involvement. "For serologically defined colon cancer antigen 8 (SDCCAG8), recessive mutations in the SDCCAG8 gene can cause a nephronophthisis-related ciliopathy with Bardet-Biedl syndrome-like features, and SDCCAG8 appears to interact with APOL1 to modulate the risk for nondiabetic end-stage kidney disease." (PMID 38898508, 2024).
breast invasive carcinoma (1 paper, 2025). "The results indicated significantly higher APOL1 levels in breast invasive carcinoma, colon adenocarcinoma, HNSC, kidney renal clear cell carcinoma, kidney renal papillary cell carcinoma, stomach adenocarcinoma and THCA." (PMID 41378287, 2025).
colon cancer (1 paper, 2023). "Moreover, we transfected RKO colon cancer cells with APOL1-KO, APOL2-KO, APOL3-KO, APOL4-KO and APOL6-KO." (PMID 36923931, 2023).
conduction disorders (1 paper, 2026). "Moreover, Stage 3 and 5 CKDs are mediators of APOL1‐related conduction disorders." (PMID 41541644, 2026).
Cryptococcal meningitis (1 paper, 2021). Meningeal inflammation produced by cryptococcus neoformans, an encapsulated yeast that tends to infect individuals with acquired immunodeficiency syndrome and other immunocompromised states. "There is some evidence that variant APOL1 confers partial protection against multiple fungal pathogens, with nonsignificant protective trends for Pneumocystis carinii pneumonia and esophageal candidiasis and a significant protective association with Cryptococcal meningitis (P = 0.03)." (PMID 33674766, 2021).
diabetic maculopathy (1 paper, 2023). Diabetic maculopathy (DM) is a type of diabetic retinopathy and it is a major eye complication and visual impairment amongst people with diabetes. "For the index SNP at the APOL1 locus found in this GWAS (rs2239785), we saw an association with diabetic maculopathy with the same direction of effect as the primary DME GWAS (OR = 1.17, P = 5.5x10-5, MAFcases = 0.18, MAFcontrols = 0.16; N = 2,790 cases, 284,826 controls)." (PMID 37585454, 2023).
diabetic retinopathy (1 paper, 2023). "We did not see an association for the APOL1 and ANKLE1/PLVAP SNPs with baseline Diabetic Retinopathy Severity Score (DRSS) (N = 1,168; P>0.1)." (PMID 37585454, 2023).
frontotemporal lobe dementia (1 paper, 2023). "Apolipoprotein L1 (APOL1) is found in the CSF of patients affected by frontotemporal lobe dementia, and in our samples it was present only in CS." (PMID 37627098, 2023).
gastroenteritis (1 paper, 2024). An inflammatory disorder that affects the upper and lower gastrointestinal tract. "Our study extends the range of infectious in which outcomes are associated with APOL1 genotype to viral pneumonia and gastroenteritis." (PMID 38360481, 2024).
HCMV infection (1 paper, 2023). "As expected, UL23 significantly restricted IFN-γ-induced gene expressions of APOL1, CMPK2, and LGALS9; UL23 also significantly reduced their expression during HCMV infection." (PMID 37112994, 2023). "To validate the transcriptomic data, we performed quantitative real-time PCR (RT-qPCR) and immunoblot to analyze the effect of ectopically expressed UL23 on the expression of APOL1, CMPK2, and LGALS9 upon IFN-γ stimulation or HCMV infection." (PMID 37112994, 2023).
hypertriglyceridemia (1 paper, 2019). A laboratory test result indicating elevated triglyceride concentration in the blood. "In nondiabetic volunteers, high BMI, hypertriglyceridemia, and low HDL-C were identified as independent characteristics that determined serum ApoL1 levels and are typical features associated with Mets." (PMID 31619724, 2019).
hypertrophy (1 paper, 2014). Hypertrophy is the increase in the volume of an organ or tissue due to the enlargement of its component cells. "A recent study in autopsies showed that APOL1 risk allele carriers presented glomerular and kidney hypertrophy and accelerated nephron loss when compared to controls." (PMID 24658608, 2014).
Immunodeficiency (1 paper, 2018). Failure of the immune system to protect the body adequately from infection, due to the absence or insufficiency of some component process or substance. "APOL1 gene expression is regulated by inflammatory cytokines that are abundantly present in people with uncontrolled HIV viraemia, immunodeficiency, and (opportunistic) infections, the classical setting in which HIVAN is diagnosed in the UK." (PMID 29982487, 2018).
intrauterine growth restriction (1 paper, 2024). "Both BAC/APOL1 and Alb/APOL1 models showed that fetal APOL1-G1 induced preeclampsia with gestational hypertension and intrauterine growth restriction, indicating placental dysfunction." (PMID 39803524, 2024).
kidney cancer (1 paper, 2022). Primary or metastatic malignant neoplasm involving the kidney. "Future studies are necessary to determine the association of APOL1 G1 and G2 RV with kidney cancer in Sub-Saharan and African-American populations compared to populations of European ancestry." (PMID 35159001, 2022). "Future studies related to such a role executed by APOL1 may shed light on the regulation of EMT in kidney cancer and be useful for devising therapeutic avenues for kidney-related cancers." (PMID 35159001, 2022).
Kidney Cyst (1 paper, 2024). Abnormal fluid filled sac within the kidney, either acquired or congenital. "Although a kidney biopsy was not done to rule out FSGS lesion, the patient was referred for kidney cysts which is not a common APOL1-related finding." (PMID 38790019, 2024).
lung carcinoma (1 paper, 2025). "To explore the role of APOL1 in LUAD, we investigated the expression level of APOL1 in TCGA-LUAD and CPTAC-LUAD; then, we conducted the cell viability assay employing A549 and H1299 lung cancer cell lines." (PMID 40649778, 2025).
lymph node metastasis (1 paper, 2021). "APOL1 expression was significantly associated with pathological stage (P = 0.031), T stage (P = 0.041), lymph node metastasis (P = 0.019), and distant metastasis (P = 0.024)." (PMID 34341330, 2021). "Univariate analysis revealed that APOL1 expression, pathological stage, T stage, lymph node metastasis, and distant metastasis were also related to OS." (PMID 34341330, 2021).
lymphoma (1 paper, 2023). A malignant (clonal) proliferation of B- lymphocytes or T- lymphocytes which involves the lymph nodes, bone marrow and/or extranodal sites.
medullary thyroid carcinoma (1 paper, 2025). "Notably, it did not include analyses of medullary thyroid carcinoma, nor did it investigate the effects of APOL1 on specific immune cell populations or tertiary lymphoid structures within the tumor microenvironment." (PMID 41378287, 2025).